CRP (C-reactive protein)
Diseases named in the same sentence as CRP in open-access papers (continued):
Sharing a sentence is not in itself a finding about the gene and the disease.
COVID-19 (continued). "COVID-19 inflammatory markers were done for all the patients which included C-reactive protein (CRP), lactate dehydrogenase (LDH), D-dimer, ferritin, CK-MB and interleukin-6 (IL-6)." (PMID 35664398, 2022). "CRP is a marker of pathogen-driven pulmonary inflammation, embolism, and disseminated intravascular coagulation, all characteristics of COVID-19, and therefore CRP is a predictive marker of adverse health outcomes." (PMID 34744161, 2022). "In an observational study in Spain, the authors found that hemodialysis patients with COVID-19 who died had lymphopenia, increased C-reactive protein and lactate dehydrogenase, and a longer time on hemodialysis treatment." (PMID 40115367, 2022). "Recent studies have focused on the role of serum inflammatory markers that predict COVID-19, such as lymphocyte counts and C-reactive protein (CRP), homocysteine, and D-dimer levels, and their correlation with serum vitamin D level." (PMID 35754946, 2022). "Some pooled data have suggested that the emergence of severe COVID-19 was related to higher levels of D-dimer and C-reactive protein (CRP) that arises after the augmentation in NLR in critically ill COVID-19 cases." (PMID 35566589, 2022). "Lower than normal absolute lymphocyte count, higher neutrophil to lymphocyte ratio, and elevated than normal CRP, ESR levels are significantly associated with a higher mortality rate in hospitalized COVID-19 patients." (PMID 35883172, 2022). "LDH, ferritin, D-dimer, and hs-CRP were found to be significantly higher in moderate and severe groups than in the mild COVID-19 group." (PMID 36475201, 2022). "Certain inflammatory markers which include ferritin, procalcitonin, and C-reactive protein were significantly higher when patients with coinfection of COVID-19 and gynaecological cancer were admitted to the hospital." (PMID 36299504, 2022). "We analysed inhibition of C-reactive protein (CRP) – a biomarker for IL-6 activity – in patients with COVID-19 or idiopathic multicentric Castleman disease (iMCD) treated with tocilizumab (anti-IL-6R) or siltuximab (anti-IL-6), respectively." (PMID 35928820, 2022). "They concluded that cortisol is a better predictor of COVID-19-related laboratory markers such as CRP, D-dimer, and neutrophil-to-lymphocyte ratio (NLR)." (PMID 36016249, 2022). "Recent studies indicate that CRP levels in COVID-19 patients who were severely ill or died were significantly higher than those in surviving patients." (PMID 35256885, 2022). "Compared with moderate correlation between CRP and IL-6 observed in COVID-19 patients, the correlations of NP levels with either CRP or IL-6 were weak." (PMID 35529699, 2022). "The best regression model obtained showed that body mass index (BMI) (P=0.025) and circulating levels of creatinine (P=0.043), CRP (P=0.039), D-dimer (P<0.001) and pyruvate (P<0.001) were the main determinants of COVID-19 severity." (PMID 36189213, 2022). "Several vital signs and laboratory results were associated with serious outcomes in COVID-19 patients in this study, with the strongest associations observed for LDH, D-dimer, and CRP." (PMID 35488229, 2022). "In COVID-19 patients with a secondary outcome, all investigated inflammatory biomarkers were significantly higher compared to event-free survivors, e.g., CRP 112.1 mg/l (IQR 47.6–162.0) vs. 15.1 mg/l (IQR 1.6–46.5), p<0.001." (PMID 35622838, 2022). "Immunologic findings in patients with COVID-19 include elevated serum C-reactive protein and pro-inflammatory cytokines (e.g., IL-6) and decreased total blood lymphocyte counts." (PMID 35646985, 2022). "Our data showed that ferritin, CRP, D-dimers, alongside the lymphocyte and neutrophil counts, contributed to COVID-19 disease severity." (PMID 35996506, 2022). "An immune response to COVID-19 increases the CRP, PCT, and SF, among other indicators, especially in critically ill individuals." (PMID 35062284, 2022).
COVID-19 (continued). "Increased levels of WBC, neutrophils, CRP, ferritin, LDH, d-dimer, and IL-6, as well as decreased levels of lymphocytes, monocytes, and albumin have been associated with severe COVID-19 and worse outcomes." (PMID 35160073, 2022). "In order to conclusively prove that CRP apheresis is the therapy of choice in severe COVID-19 courses, randomized controlled trials are urgently needed." (PMID 35407564, 2022). "In hospitalized older adults with COVID-19, tomographic pulmonary involvement > 50%, anemia, vitamin D below 40 ng/mL, and CRP above 80 mg/L are independent factors for progression to severe respiratory failure and the need for mechanical ventilation." (PMID 35172759, 2022). "In patients with COVID-19, QTc interval at admission were demonstrated to correlate with CRP levels, reflecting the inflammatory status." (PMID 35811696, 2022). "Biomarkers such as C-reactive protein (CRP), interleukin (IL)-8, interleukin-10 (IL-10) and tumor necrosis factor (TNF)-α are all considered as diagnostic biomarkers for COVID-19 patients in clinic." (PMID 36343035, 2022). "CRP and other cytokines have been widely studied in COVID-19, with correlation to a more severe disease, lung damage, and mortality." (PMID 35897672, 2022). "Multivariate analysis showed that older age, male gender, comorbidities such as DM, active malignancy, white cell count, serum creatinine, albumin, and CRP were independent predictors of hyponatremia in patients with COVID-19 (P < 0.001, for all)." (PMID 36714113, 2022). "The bulk of asymptomatic carriers who developed symptoms and most of the COVID-19 patients were older than 18 years of age with a decreased lymphocyte count, abnormal hepatic and renal function, and increased D-dimer and C-reactive protein." (PMID 36620481, 2022). "Some studies identify the role of proinflammatory markers such as CRP, interleukine-6, and neutrophil count in the prediction of a worse prognosis in patients with COVID-19." (PMID 36465942, 2022). "Inflammatory markers, such as IL-6, D-dimer, CRP, and/or ferritin, are believed to correlate directly with mortality in COVID-19." (PMID 36289811, 2022). "Another retrospective cohort study was conducted on 29 patients with COVID-19-induced ARDS with hyper inflammation (CRP ≥ 100 mg/L)." (PMID 35619180, 2022). "This inflammatory reaction induces the production of several defense proteins such as CRP and ferritin in the liver, which further enhance inflammation and sustain the cytokine storm in severe COVID-19 patients (Ruscitti and others 2020; Meng and others 2021)." (PMID 35647937, 2022). "Several studies have tried to determine the feasibility of using hematological indices to predict severity of disease and mortality in COVID-19 patients alongside other markers, such as CRP and ferritin." (PMID 36556258, 2022). "Afterward, in the COVID-19 patients who survived the disease, CRP levels were found to gradually decrease in the disease course, with the biggest change being observed during the first half of hospitalization." (PMID 35495660, 2022). "COVID-19 patients in the first wave showed higher maximum CRP (190.8 ± 133.3 vs. 99.1 ± 97.8 mg/L; p < 0.01), higher percentage of patients with pulmonary embolism (20 vs. 8%; p = 0.03)) in comparison to patients in the second wave." (PMID 37726605, 2022). "In terms of laboratory parameters, inflammatory biomarkers such as CRP or ESR are extremely useful for assessing the severity of both COVID-19 and PIMS and to monitor their clinical course." (PMID 36138657, 2022). "A retrospective cohort study of 2052 hospitalized patients with COVID-19 showed that inflammatory factors (highly sensitive CRP, procalcitonin) and cytokines (IL-2R, IL-6, IL-8) were higher in cancer patients compared with noncancer patients." (PMID 36033814, 2022).
COVID-19 (continued). "The lipoprotein dyslipidemia associated with COVID-19 severity (high TG and low total, LDL and HDL cholesterol) was inversely correlated with inflammatory biomarkers such as increased levels of serum CRP, IL-6, IL-8, and IL-10." (PMID 35956081, 2022). "Previous reports have proposed the use of serum CRP, D-dimer, procalcitonin, and ferritin as indices for predicting the prognosis of COVID-19." (PMID 36226145, 2022). "The National Health Commission of the People's Republic of China included elevated inflammatory factors such as IL-6 and CRP aspotential early warning indicators of severe disease in its widely used "COVID-19 diagnosis and treatment plan"." (PMID 35539890, 2021). "Although this pilot study relies on a small cohort, our data suggests a central role for CRP in the timing of COVID-19 immunopathology by marking the turning point of longitudinal NLR dynamic and thereby providing a window for maximal subgroup distinction." (PMID 34307391, 2021). "It is reported that a marked increase in inflammatory factors occurs in COVID-19, including C-reactive protein (CRP), IL-6, TNF-α, etc.." (PMID 34335279, 2021). "In the second model, including all candidates’ predictors, except COVID-19, only CRP at peak (HR 1.01, CI95% [1.00–1.02], p = 0.029) was independently associated with transfer to the ICU." (PMID 34064556, 2021). "In the cohort we studied, admission to intensive care unit was associated with decreased mortality while older age, use of remdesivir, and high levels of CRP and LDH were associated with increased mortality in COVID-19 patients." (PMID 34692345, 2021). "The high surge of IL6, IL1b, IFNγ, C-reactive protein, and TNF-α senescence leads to lower airway and lung injury and increased risk for COVID-19 in elderly patients." (PMID 33815889, 2021). "The ROC curve was used to make positive and negative predictions, suggesting that increases in Alb and Hct but decreases in CRP, PCT, LDH, HBDH, and ESR were more susceptible to COVID-19 (p < 0.001)." (PMID 34859002, 2021). "We identified anemia, thrombocytopenia, strongly elevated levels of LDH (> 2 × ULN) and CRP (> 30 mg/dl) at initial presentation as factors predicting a severe course of COVID-19 in patients with pre-existing renal impairment." (PMID 33851328, 2021). "CRP and ferritin are acute phase reactants that have been established to be the biomarkers of hyper inflammation condition in COVID-19." (PMID 34744508, 2021). "Also, the combination of eosinopenia and increased high-sensitivity C-reactive protein (hs-CRP) can serve to distinguish between patients suspected of presenting COVID-19 (supporting the diagnostic process) from patients with pneumonia or a respiratory infection similar to COVID-19." (PMID 33776561, 2021). "For this analysis, COVID-19 patients were grouped in four quartiles according to CRP: CRP1 (< 29.1 mg/L, n = 12); CRP2 (29.1–73.7 mg/L, n = 12); CRP3 (73.7–118.0 mg/L, n = 10), and CRP4 (> 118.0 mg/L, n = 10)." (PMID 34737330, 2021). "Se biomarkers were correlated with reduced parameters of inflammation, especially CRP, which has been identified as a reliable predictor of disease severity and outcome in COVID-19." (PMID 34203015, 2021). "In the present study, we investigated the effects of dexamethasone and tocilizumab treatment on PCT and CRP kinetics, as well as the values of these inflammatory biomarkers for early detection of secondary infections in critically ill COVID-19 patients." (PMID 34353339, 2021). "Consistent with this, COVID-19 patients demonstrate up-regulated C-reactive protein level, the elevated level of interleukin 6 (IL-6), increased neutrophil counts, and decreased lymphocyte counts." (PMID 33806290, 2021). "Serum LPS and zonulin were higher in patients with COVID-19 than in control subjects; in COVID-19, LPS significantly correlated with zonulin (Rs = 0.513; P < 0.001) and hs-CRP (Rs = 0.544; P < 0.001)." (PMID 34092777, 2021).
COVID-19 (continued). "As expected, the markers of inflammation, such as CRP, IL-6, or ferritin, were significantly higher in COVID-19 patients with pneumonia." (PMID 34680053, 2021). "This study also compared the role of vitamin D in coagulopathy with other surrogate markers reported previously associated with COVID-19 severity, such as ferritin, lactate dehydrogenase (LDH), neutrophil-lymphocyte ratio (NLR), CRP, and APL-Abs." (PMID 34744508, 2021). "The univariate model showed that severe COVID-19 patients were more likely to be men and to have elevated blood levels of C-reactive protein (CRP) compared with mild to moderate COVID-19 patients." (PMID 34349747, 2021). "E.g., in COVID-19, median CRP levels were 15.6 mg/dL (IQR 1.6–46.7) in event-free survivors as compared to 112.6 mg/dL (IQR 47.6–162.7) in patients with the primary composite outcome (p < 0.001)." (PMID 34204453, 2021). "We also confirmed the prognostic value of RDW for short-term mortality in COVID-19 across several sub-groups, including age, gender, arterial hypertension, history of cardiovascular disease, anemia, increased CRP and creatinine (P < 0.05 in all sub-groups)." (PMID 33816532, 2021). "High CRP levels in COVID-19 patients (due to inflammatory reaction and tissue destruction) indicate a more severe illness and worse prognosis with lung damage." (PMID 34721903, 2021). "In an analysis of 1835 patients across 13 hospital sites using a binary cut-off for CRP as a prognostic factor of COVID-19, inpatient death appeared to have similar predictive power compared with treating it as a linear or Ln(CRP)." (PMID 33683344, 2021). "The aim of this study is to examine the CRP response in patients hospitalized with COVID-19 and to determine the utility of CRP on admission for predicting inpatient mortality." (PMID 33683344, 2021). "In COVID-19 patients, IL-6 concentration directly correlated with IL-10 levels (r = 0.48, p < 0.01) and CRP levels directly correlated with N/L ratio (r = 0.37, p = 0.04)." (PMID 33808205, 2021). "COVID-19 is known to have a specific constellation of laboratory findings including decreased albumin, high CRP, high LDH, lymphopenia, and high ESR." (PMID 33627147, 2021). "Contrasted with the imported COVID-19 patients with BMI < 24, high proportion of COVID-19 patients with BMI ≥ 24 in our study, especially those with elevated CRP and LDH, developed to severe type, with longer hospitalization duration and anti-virus course." (PMID 33546633, 2021). "The most common clinical abnormalities observed in COVID-19 positive patients are lymphopenia, leukopenia, thrombocytopenia, elevated CRP and inflammatory markers, elevated cardiac biomarkers, decreased albumin, and abnormal renal and liver function." (PMID 34093642, 2021). "In contrast, CRP and ferritin were significantly higher in COVID-19 than in controls, suggesting higher inflammatory activity in COVID-19 at time of ED presentation in." (PMID 34204453, 2021). "The level of C-reactive protein (CRP) was 25.0 mg/L in patients with influenza-A, which was five times higher than that in patients with COVID-19 (p < 0.001)." (PMID 34859002, 2021). "Cluster C, with 149 individuals, had the lowest number of COVID-19 patients and the lowest levels of almost all indicators, including CRP and symptoms, among the three clusters." (PMID 34336871, 2021). "Further correlation analysis suggested a significant correlation between hs-CRP and systolic blood pressure in patients with COVID-19." (PMID 34789776, 2021). "In these 395 COVID-19 patients, Hs-CRP (5.0 [2.2–22.9] mg/L) and PCT (0.05 [0.03–0.08] ng/ml) levels were elevated, while lymphocytes, CD4+T and CD8+T cell levels were all within the standard ranges." (PMID 33435865, 2021). "Although several studies have noticed the correlation between CRP and COVID-19 severity in patients with CVD, its potential significance in various CVD types is lacking and needs to be further investigated." (PMID 34447386, 2021).
COVID-19 (continued). "Using Tocilizumab (TCZ), a human IL-6 blockade agent, indicated a reduction in lung lesion opacity, oxygen demand, decrease in C-reactive protein, and normalization of lymphocytes count in 90.5, 75, 84.2, and 52.6% in COVID-19 patients, respectively." (PMID 33761870, 2021). "The massive elevation of cytokines in severe COVID-19 is also accompanied by elevated circulating levels of innate soluble receptors, such as C-reactive protein (CRP), pentraxins, and complement fragments." (PMID 34641348, 2021). "For hospitalized patients inflammation markers such as C-reactive protein were assessed during ongoing COVID-19 two weeks prior to study enrollment." (PMID 34867933, 2021). "Partially their observations were consistent with our findings, showing significant increases in ALT, AST, LDH, CRP, and coagulation tests in severe COVID-19 cases and a decrease in albumin, when compared to mild cases of infection." (PMID 34200570, 2021). "This study firstly investigated the correlation between the viral load and part of the blood routine indexes (neutrophil and lymphocyte count) and CRP in COVID-19 patients." (PMID 34122620, 2021). "During the first wave, we modelled data on CRP over time in COVID-19 patients finding that it performed better than SpO2/FiO2." (PMID 34764169, 2021). "We used the receiver operating characteristic (ROC) curve to show sensitivity as a function of 100%—specificity, determining a CRP threshold of hospitalizations among patients with suspected COVID-19, derived from the observed data." (PMID 35011944, 2021). "For other parameters, a rise in ferritin, C-reactive protein, erythrocyte sedimentation rate and glucose levels were found in 37.92%, 36.08%, 27.37% and 36.48% of the COVID-19 cases, respectively." (PMID 33520252, 2021). "In COVID-19 patients, increased neutrophils/CRP and decreased lymphocytes were revealed; this was in direct correlation with disease severity." (PMID 34068970, 2021). "In early clinical studies, tocilizumab significantly improved several outcomes in severe and critical COVID-19 cases, including supplemental oxygen utilization and C-reactive protein and D-dimer levels." (PMID 33584343, 2021). "In this study, we found inflammatory markers such as CRP, hs-CRP were significantly increased in hypertensive-COVID-19." (PMID 34789776, 2021). "CRP-mediated complement- and macrophage activation is suspected to be the main driver of pulmonary fibrosis and subsequent organ failure in COVID-19." (PMID 34408751, 2021). "The SMACORE study used baseline criteria for administration of tocilizumab of CRP >50 mg/l, procalcitonin <0.5 ng/mL and P/F ratio <300 mmHg in seriously ill COVID-19 patients." (PMID 33763201, 2021). "Similar conclusions can also be drawn from a recent study, where patients with SMD including schizophrenia who were hospitalised for severe COVID-19 had high levels of inflammatory biomarkers such as CRP, IL-6, D-dimer and ferritin, on admission." (PMID 34079487, 2021). "Biomarkers to distinguish disease progression in COVID-19 include interleukin (IL)-6, C-reactive protein (CRP), D-dimers and lactic dehydrogenase (LDH), yet our understanding of their role in disease pathophysiology remains limited." (PMID 34471264, 2021). "COVID-19 patients with elevated levels of CRP need close monitoring and early treatment even in the absence of severe disease as risk of progression is significant." (PMID 35076497, 2021). "CRP levels of > 41.8 mg/L were observed in 57.6% of severe COVID-19 patients, and elevated ferritin was observed in 38.3% of the same group." (PMID 34623528, 2021). "Lymphopenia, increased CRP, and erythrocyte sedimentation were observed in the laboratory results of COVID-19 patients." (PMID 34444600, 2021). "Earlier reports have also indicated that CRP levels at the time of admission and prior to discharge or death are markers of poor prognosis in patients with COVID-19." (PMID 34868744, 2021).